TMEM158 (transmembrane protein 158)
Diseases named in the same sentence as TMEM158 in open-access papers (continued):
Sharing a sentence is not in itself a finding about the gene and the disease.
tumor (continued). "Therefore, TMEM158 expression is frequently altered in most of human cancer types, indicating a potential functional role in carcinogenesis or disease progression as an oncogenic factor or tumor suppressor depending on the tumor types." (PMID 36387246, 2022). "Some of TMEM proteins act as tumor suppressors such as TMEM7, TMEM25, TMEM97, and TMEM176A; while a large number of them act as oncogenes such as TMEM14A and TMEM158." (PMID 37335919, 2023). "The present study confirmed its expression profile in TNBC, showing that TMEM158 overexpression mediates EMT by mobilizing the TGF-β pathway and thereby participating in tumor adhesion and invasion." (PMID 35711843, 2022). "Bioinformatics analysis revealed that TMEM158 was overexpressed in TNBC and related to tumor progression." (PMID 35711843, 2022). "To apply these data for clinical consultation, we constructed a prognostic calculating table, which integrated clinicopathological information (Tumor stage, PSA level, Gleason score, lymph node invasion) and TMEM158 expression level." (PMID 36387246, 2022). "Strategies focused on down-regulating TMEM158, Mybl1, IL32, ETS1 and PTX3 should be considered to determine their effect on TNBC tumor progression." (PMID 28966727, 2017). "According to the data of TCGA and TCGA-GTEx, the TMEM158 content was increased in GC tumor tissues compared with normal controls." (PMID 37970923, 2023). "Furthermore, some of these proteins act as tumor suppressors (e.g., TMEM25, TMEM7) while others act as pro-oncogenes (e.g., TMEM158, TMEM14A...)." (PMID 30574087, 2018). "Furthermore, we suggest that the dynamic change of ANO1, TMEM38B, TMEM158, and TMEM45A may indicate stellate cell activation and trigger tumor stromal remodeling." (PMID 37265785, 2023). "In addition, TMEM158 expression was strongly correlated with R-Ras but not K-Ras or N-Ras gene expression and anti-tumor immune infiltration." (PMID 36387246, 2022).
cancer (19 papers, 2008 to 2026). A tumor composed of atypical neoplastic, often pleomorphic cells that invade other tissues. "On the other hand, the expression of TMEM158 has been reported to be upregulated in multiple types of cancer and has been associated with an oncogenic function." (PMID 37936608, 2023). "On the other hand, in over 20 types of cancer TMEM158 is associated with cancer-associated fibroblast infiltration." (PMID 37936608, 2023). "TMEM158 plays an important role in many cancers since it is upregulated in the renin-angiotensin system (Ras)-induced senescence process." (PMID 37064154, 2023). "In the present study, we first found that TMEM158 expression was significantly altered in 24 cancers, especially GBM." (PMID 34992215, 2022). "On the other hand, in vitro siRNA knockdown of TMEM158 have resulted in the inhibition of cell proliferation and increased apoptosis in cancer cells." (PMID 34044804, 2021). "Together these data support the association of MYBL1, IL32, TMEM158 and ETS1 with certain TNBCs and the enrichment of genes involved in immune related processes as differentially associated with the cancers." (PMID 28966727, 2017). "Gene pool enrichment analysis of the GSA gene pool demonstrated that TMEM158 plays an essential role in the cancer immune response and could be considered a potential therapeutic target to modulate the immune system in cancer patients." (PMID 37936608, 2023). "TMEM158 plays an imperative role in the prognosis and regulation of various cancers." (PMID 37970923, 2023). "In addition, the HE assay revealed that cancer cells were loosely arranged, and nuclei were pyknotic and fragmented in the sh-TMEM158 group." (PMID 37970923, 2023). "A recent pan-cancer study where TMEM158 expression levels were analyzed in 33 types of cancer using the TCGA and Genotype-Tissue Expression (GTEx) databases suggests that TMEM158 may have distinct biological functions in various cancer tissues." (PMID 37936608, 2023). "Transmembrane protein 158 (TMEM158) has been proven to be an important cancer regulator." (PMID 37970923, 2023). "It was reported that TMEM158 enhanced proliferation and migration of cancer cells." (PMID 35355981, 2022). "First, we analyzed the expression profile of TMEM158 across cancers." (PMID 34992215, 2022). "This indicates that TMEM158 likely plays an important role in GBM compared to other cancers." (PMID 34992215, 2022). "Therefore, TMEM158 becomes a promising therapeutic target or prognostic biomarker that should continue to be studied until its role is fully understood in the different types of cancer where it has been differentially expressed." (PMID 37936608, 2023). "Furthermore, there is evidence that TMEM158 may be involved in chemotherapeutic sensitivity and cancer progression by activating signaling pathways such as TGF1 and PI3K/AKT." (PMID 37936608, 2023). "Out of 52 genes investigated, we observed that many genes upregulated in M2 and downregulated in M1 macrophages–ACTN1, FLRT2, MRC1, PTGS1, RHOJ, TMEM158–correlated positively with the EMT scores (first 6 rows) across multiple cancer types." (PMID 30729096, 2019). "TMEM158 expression values in 33 types of cancers were extracted from TCGA database and compared to TMEM158 expression values in tissues from non-lesion sites obtained from GTEx database." (PMID 34992215, 2022). "The contribution of TMEM158, KIF18A, and SLC39A1 to cell proliferation or cancer progression was established already, but how exactly they integrate in the YAP signaling pathway is currently unknown." (PMID 33514403, 2021). "Furthermore, while a functional genetic interaction between YAP and TRAM2, KIF18A, TMEM158, and SLC39A1 was never reported, the role of TMEM158, KIF18A, and SLC39A1 in cell proliferation or cancer progression was already established before." (PMID 33514403, 2021).
TMEM158 also shares sentences with these, for which no sentence is quoted: colon cancer (2 papers); adrenocortical carcinoma (1); anaplastic thyroid carcinoma (1); bladder urothelial carcinoma (1); esophageal carcinoma (1); gallbladder cancer (1); gastric cancer (1); head and neck squamous cell carcinoma (1); lung adenocarcinoma (1); oligodendroglioma (1); rectal cancer (1); rectum adenocarcinoma (1); sarcoma (1); squamous cell carcinoma (1); stomach adenocarcinoma (1); testicular germ cell tumor (1); thymoma (1); uterine corpus endometrial carcinoma (1); viral infection (1).